BIRC2 (baculoviral IAP repeat containing 2)
Description:
Multi-functional protein which regulates not only caspases and apoptosis, but also modulates inflammatory signaling and immunity, mitogenic kinase signaling, and cell proliferation, as well as cell invasion and metastasis. Acts as an E3 ubiquitin-protein ligase regulating NF-kappa-B signaling and regulates both canonical and non-canonical NF-kappa-B signaling by acting in opposite directions: acts as a positive regulator of the canonical pathway and suppresses constitutive activation of non-canonical NF-kappa-B signaling. The target proteins for its E3 ubiquitin-protein ligase activity include: RIPK1, RIPK2, RIPK3, RIPK4, CASP3, CASP7, CASP8, TRAF2, DIABLO/SMAC, MAP3K14/NIK, MAP3K5/ASK1, IKBKG/NEMO, IKBKE and MXD1/MAD1. Can also function as an E3 ubiquitin-protein ligase of the NEDD8 conjugation pathway, targeting effector caspases for neddylation and inactivation. Acts as an important regulator of innate immune signaling via regulation of Toll-like receptors (TLRs), Nodlike receptors (NLRs) and RIG-I like receptors (RLRs), collectively referred to as pattern recognition receptors (PRRs). Protects cells from spontaneous formation of the ripoptosome, a large multi-protein complex that has the capability to kill cancer cells in a caspase-dependent and caspase-independent manner. Suppresses ripoptosome formation by ubiquitinating RIPK1 and CASP8. Can stimulate the transcriptional activity of E2F1. Plays a role in the modulation of the cell cycle.
Synonyms: C-IAP1; hIAP-2; hIAP2; API1; MIHB; RNF48; cIAP1; IAP-2
Tractability: Small molecule: a drug acting on it is in phase 2 or 3 trials; a structure with a bound ligand is known; a high-quality ligand is known; it has a high-quality binding pocket; it belongs to a druggable protein family. PROTAC: UniProt records ubiquitination sites on it; ubiquitination databases record sites on it; its protein half-life has been measured; a small molecule that binds it is known.
Target class: Enzyme
Chemical probes: ASTX-660, PD008537, PD053062, PD070483, PD070484, PD070486, PD070487, PD070491, PD070492, PD070493, PD081149, PD081187, PD081243, PD081362, PD081617, PD082089, PD082269, PD082355, PD082401, PD082542, and 39 more
Gene: Protein-coding gene on chromosome 11 (102,347,208 to 102,378,680, forward strand). Ensembl gene ENSG00000110330.
Subcellular location: Cytoplasm; Nucleus
Subcellular location (Human Protein Atlas): Cytosol; Nucleoli fibrillar center; Nucleoplasm
Pathways (Reactome):
Immune System: IKK complex recruitment mediated by RIP1; NOD1/2 Signaling Pathway; TICAM1, RIP1-mediated IKK complex recruitment; TNF receptor superfamily (TNFSF) members mediating non-canonical NF-kB pathway; TNFR2 non-canonical NF-kB pathway
Programmed Cell Death: Apoptotic cleavage of cellular proteins; RIPK1-mediated regulated necrosis; Regulation of necroptotic cell death
Signal Transduction: Regulation of TNFR1 signaling; TNFR1-induced NF-kappa-B signaling pathway; TNFR1-induced proapoptotic signaling
Cell-Cell communication: Activation of STAT3 by cadherin engagement
Metabolism of proteins: Ub-specific processing proteases
Gene Ontology:
Molecular function: FBXO family protein binding; identical protein binding; protein binding; protein-folding chaperone binding; transcription coactivator activity; transferase activity; ubiquitin binding; ubiquitin-protein transferase activity; zinc ion binding; cysteine-type endopeptidase inhibitor activity involved in apoptotic process; ubiquitin protein ligase activity; protein-containing complex binding
Biological process: negative regulation of apoptotic process; positive regulation of canonical NF-kappaB signal transduction; positive regulation of protein K48-linked ubiquitination; positive regulation of protein K63-linked ubiquitination; positive regulation of protein monoubiquitination; proteasome-mediated ubiquitin-dependent protein catabolic process; protein polyubiquitination; regulation of apoptotic process; regulation of cell cycle; regulation of necroptotic process; canonical NF-kappaB signal transduction; cell surface receptor signaling pathway; extrinsic apoptotic signaling pathway via death domain receptors; inflammatory response; intrinsic apoptotic signaling pathway in response to DNA damage; negative regulation of necroptotic process; non-canonical NF-kappaB signal transduction; positive regulation of protein ubiquitination; regulation of cell differentiation; regulation of cell population proliferation; regulation of inflammatory response; regulation of innate immune response; regulation of nucleotide-binding domain, leucine rich repeat containing receptor signaling pathway; regulation of RIG-I signaling pathway; regulation of toll-like receptor signaling pathway; and 7 more
Cellular component: cytoplasm; cytosol; nucleoplasm; nucleus; survivin complex; CD40 receptor complex; cytoplasmic side of plasma membrane; plasma membrane; tumor necrosis factor receptor superfamily complex; protein-containing complex; XY body
Genetic constraint (gnomAD): Loss-of-function variants: 13 observed, 54.31 expected, observed/expected ratio (o/e) 0.24, 90% interval 0.16 to 0.38. The upper end of that interval is the gene's LOEUF score, 0.38, which puts it in group 1 of 6, group 1 being the genes least tolerant of losing a copy. Missense variants: 662 observed, 715.41 expected, observed/expected ratio (o/e) 0.93, 90% interval 0.87 to 0.99. Synonymous variants: 265 observed, 248.39 expected, observed/expected ratio (o/e) 1.07, 90% interval 0.96 to 1.18.
Homologues: Orthologues: chimpanzee BIRC2 (99% identical), macaque BIRC2 (98% identical), dog BIRC2 (89% identical), guinea pig BIRC2 (88% identical), pig BIRC2 (87% identical), rabbit BIRC2 (84% identical), mouse Birc2 (83% identical), rat Birc2 (79% identical), tropical clawed frog birc2 (57% identical), zebrafish birc2 (56% identical), Drosophila melanogaster Diap2 (27% identical), Caenorhabditis elegans bir-2 (12% identical). Paralogues in human: BIRC3 (71% identical), XIAP (31% identical), BIRC6 (29% identical), NAIP (27% identical), BIRC7 (19% identical), NLRC4 (13% identical), BIRC5 (8% identical).
Diseases named in the same sentence as BIRC2 in open-access papers:
BIRC2 is named in the same sentence as 135 diseases in open-access papers, as found by Europe PMC text mining. Sharing a sentence is not in itself a finding about the gene and the disease. The quoted sentences say what the papers report.
breast carcinoma (50 papers, 2009 to 2025). "It is of interest that overexpression of BIRC2 has been recently proposed to be associated with luminal subtype B of breast cancer." (PMID 22040021, 2011). "BIRC2 is highly expressed in various tumours, including breast cancer, melanoma, glioblastoma, gallbladder cancer and nasopharyngeal carcinoma, and plays a crucial role in the escape of tumour cells from apoptosis." (PMID 38538582, 2024). "Studies have reported that BIRC2 knockdown increased the sensitivity of mouse melanoma cells and breast cancer cells to immune checkpoint inhibitors." (PMID 34681681, 2021). "In breast cancer and melanoma, we demonstrated that HIF-dependent expression of BIRC2 led to decreased CXCL9 expression, which prevented the recruitment of CD8+ T cells and NK cells to the tumor." (PMID 35499076, 2022). "Much progress has been made in understanding the mechanism of BIRC2 and BIRC3 in multiple cancers, including liver cancer, chronic lymphocytic leukaemia, breast cancer and ovarian cancer." (PMID 33452764, 2021). "Bioinformatics analysis of publicly available data from the TCGA database confirmed statistically significant higher levels of BIRC2 (p = 0.0213), BIRC3 (p = 0.0029), BIRC5 (p = 0.0040) gene expression in breast cancer patients under 51 years of age." (PMID 33673050, 2021). "Inhibitor of apoptosis proteins or IAPs (XIAP and BIRC2), and NOTCH signaling proteins are known to be involved in anti-apoptosis process and are elevated in many cancer cells, especially breast cancer." (PMID 30513116, 2018). "Overall, this suggests that BCL2L1, BIRC2, and ACTN4 are potentially major regulators of TRAIL-induced caspase-3/7 in breast cancer and that their LOF has the potential to overcome resistance to TRAIL-induced cytotoxicity." (PMID 24745479, 2014). "Prolonged exposure of breast cancer stem cells to rottlerin results in apoptosis, which is correlated with phosphorylated AKT and MTOR suppression, phosphorylated AMPK upregulation and anti-apoptotic BCL2, BCL2L1, XIAP and BIRC2/cIAP1 downregulation." (PMID 36497321, 2022). "In addition, we observed feedback loops concerning nuclear factor kappa B subunit 1 (NFKB1) activation (CHUK, NFKBIA; related to cell survival) in bladder cancer, anti-apoptotic BIRC2/3, and pro-apoptotic TRAF1 factors in breast cancer, respectively." (PMID 28775339, 2017).
melanoma (33 papers, 2008 to 2025). A malignant, usually aggressive tumor composed of atypical, neoplastic melanocytes. "They discovered that mouse melanoma and breast tumors were significantly more sensitive to anti-CTLA4 and/or anti-PD1 ICB when there was a deficiency in the expression of BIRC2." (PMID 37781078, 2023). "In this study, the transcript levels of IAP genes including NAIP (BIRC1), BIRC2 (CIAP1), BIRC3 (CIAP2), BIRC5 (Survivin), BIRC6 (Apollon), and XIAP (BIRC4) in UA-treated A-375 melanoma cells were investigated." (PMID 39473730, 2024).
lung carcinoma (22 papers, 2010 to 2025). "For instance, loss of docking protein 2 (DOK2) as well as expression of baculoviral IAP repeat-containing 2/3 (BIRC2/3) can facilitate lung cancer cell proliferation and contribute to lung tumor development." (PMID 24650256, 2014). "Consistently, DNA amplifications of Birc2 and Birc3 have been observed in mouse liver and human lung cancers, liver carcinoma, oral squamous cell carcinoma, medulloblastoma, glioblastoma, and pancreatic cancer." (PMID 22682366, 2012). "For instance, loss of docking protein 2 (DOK2) as well as overexpression of baculoviral IAP repeat-containing 2/3 (BIRC2/3) can facilitate lung cancer cell proliferation and contribute to lung tumor development." (PMID 21935476, 2011). "To better understand the role of GSK-3α and examine the critical genes affected by GSK-3α in lung cancer, we initially screened a subset of NF-κB target genes such as MYC, WT1, BIRC2, IL-9, HMOX1, and TERT, which were regulated by a pan-GSK-3 inhibitor AR-014418 in pancreatic cancer." (PMID 27049759, 2016).
prostate carcinoma (22 papers, 2009 to 2026). A carcinoma that arises from epithelial cells of the prostate gland. "RUNX2 is a bone-specific transcriptional regulator, aberrantly expressed in metastatic prostate cancer cells and BIRC2, also known as Inhibitor of Apoptosis (IAP) plays key role in drug resistance and survival of cancer cells through inhibition of apoptosis." (PMID 31756185, 2019). "As BIRC2 (cIAP1), BIRC4 (XIAP) and BIRC5 (survivin) tended to be co-upregulated in prostate cancer in addition to BIRC6, simultaneous targeting of BIRC6 plus one of these IAP members was more likely to give superior anti-cancer effects." (PMID 25071009, 2014).
multiple myeloma (20 papers, 2011 to 2024). "The NFκB pathway was altered in 45% of HMCLs, mostly by inactivating TRAF3 (frame-shift, non-sense mutation, insertion or deletion) or BIRC2/BIRC3 (homozygous deletion) as previously reported in primary myeloma cells." (PMID 30545397, 2018). "BIRC2 (cIAP1) and BIRC3 are also frequently inactivated by copy number loss or by nonsense or frameshift mutations in multiple myeloma." (PMID 36119107, 2022). "Deletions of NFκB-pathway modulating genes TNFAIP3, BIRC2/BIRC3, TRAF3 or CYLD were identified in 16.6, 4.8, 13.9 and 16.9% of Myeloma XI cases, respectively." (PMID 28584253, 2018). "For example, BIRC2 and FAF1 are among the top 10 genes identified using DR-Integrator analysis of a paired copy number and gene expression dataset for myeloma." (PMID 23418540, 2013). "A BIRC2/BIRC3 deletion activates non-canonical NF-κB signaling in multiple myeloma, whereas 11q22 amplification (containing cIAP locus) was associated with earlier onset of disease in cervical cancer." (PMID 27167336, 2016). "Furthermore, frequent homozygous deletions of genes playing important role in myeloma biology such as TRAF3, BIRC1/BIRC2, RB1, or CDKN2C were observed." (PMID 24987674, 2014).
ovarian carcinoma (17 papers, 2012 to 2025). A malignant neoplasm originating from the surface ovarian epithelium. "Depletion of BIRC2 has been shown to enhance chemosensitivity in ovarian cancer, highlighting its potential as a therapeutic target." (PMID 40389954, 2025). "Previous studies have demonstrated the role of BIRC2 in promoting tumorigenesis and inhibiting apoptosis in several cancer types, including gallbladder cancer and ovarian cancer." (PMID 40389954, 2025). "We previously established that COL11A1 promotes cisplatin resistance in ovarian cancer cells through activation of NFkB and upregulation of specific inhibitors of apoptosis (IAPs; BIRC2, BIRC3, and XIAP)." (PMID 34638339, 2021). "We have shown that COL11A1 enhances Src/Akt/NFκB activation in human ovarian cancer cell lines, leading to upregulation of inhibitor of apoptosis protein (IAP) expression (BIRC2, BIRC3, XIAP)." (PMID 33668097, 2021). "We found that BIRC3 expression correlated inversely with ovarian cancer patient outcome, while BIRC2, BIRC4, BIRC5, and BIRC7 had no significant impact on patient outcome." (PMID 30718461, 2019). "Interestingly, this group did not see an induction of the pro-survival proteins BIRC2, BIRC3, nor Bcl-2 when COL11A1 was overexpressed in A2780 and ES2 ovarian cancer cell lines, nor a reduction of these proteins when COL11A1 expression was knocked down in A2780CP70 ovarian cancer cell line." (PMID 33668097, 2021).
cervical carcinoma (16 papers, 2004 to 2026). A carcinoma arising from either the exocervical squamous epithelium or the endocervical glandular epithelium. "Because topotecan is a recommended first-line therapy, we examined the effect of BIRC2 inhibition on cervical cancer cells treated with topotecan." (PMID 34681681, 2021). "Many of the genes, including BIRC2, BIRC3, ATF5, NUP62, FASTKD3, IDH3G, and POFUTI, have been found to be regulated by gains or losses in previous cervical cancer studies." (PMID 19911042, 2009). "The treatment of HeLa-S3 or MS751 cervical cancer cells with si-BIRC2 or varying concentrations of topotecan did not significantly affect cell apoptosis." (PMID 34681681, 2021). "However, BIRC2 knockdown significantly promoted cell apoptosis in cervical cancer cells relative to nontargeting siRNA (si-Control) after topotecan treatment." (PMID 34681681, 2021).
hepatocellular carcinoma (15 papers, 2007 to 2025). A malignant tumor that arises from hepatocytes. "The relevance of this phenomenon in cancer has been shown for the genes MMP13, Birch2, and Birch3, which are functionally related oncogenes contained on the same amplification in osteosarcoma, and for BIRC2 and YAP1, cooperating oncogenes in an amplification in hepatocellular carcinomas." (PMID 23393560, 2013).
liver cancer (11 papers, 2010 to 2026). An epithelial or non-epithelial malignant neoplasm that arises from the liver. "Our findings underscore the therapeutic potential of targeting the m1A/BIRC2 axis to overcome apoptosis resistance in liver cancer, offering new avenues for intervention in this malignancy." (PMID 41991508, 2026). "In vitro, in vivo, and clinical analyses validate the critical role of the m1A/BIRC2 axis in regulating apoptosis and tumor progression in liver cancer." (PMID 41991508, 2026).
colorectal cancer (10 papers, 2015 to 2026). A primary or metastatic malignant neoplasm that affects the colon or rectum. "Online databases Oncomine and GEPIA were used to compare the expression of IAPs (NAIP, BIRC2, BIRC3, XIAP, BIRC5/survivin, BIRC6 and BIRC7, no data on BIRC8 was available) between colorectal cancer and normal tissues." (PMID 32381104, 2020).
viral infection (7 papers, 2016 to 2023). "Since BIRC genes may play roles in cell fate following viral infection, we tested whether the viral infection-associated cytokine, IFNG, could enhance BIRC2 and/or BIRC3 expression." (PMID 37289679, 2023). "Many studies have suggested the inconsistent effects of mammalian BIRC2 in viral infection." (PMID 34887869, 2021). "The BIRC2 and BIRC3 genes (which had altered expressions in ASD, asthma, ear infection, and bacterial and viral infections) are members of the inhibitor-of-apoptosis protein family and are key regulators of NOD1 and NOD2 innate immunity signaling." (PMID 27842596, 2016). "Since BIRC2/BIRC3 and TRAF2/3 could form a cytoplasmic complex, where BIRC2/BIRC3 mediated ubiquitination and degradation of TRAF3, the roles of BIRC2/BIRC3 in viral infection were extensively investigated." (PMID 34887869, 2021). "Conversely, and despite potential roles for these two BIRCs in cell fate determination during viral infections, the antiviral cytokine, IFNG, did not acutely induce expression of either BIRC2 or BIRC3." (PMID 37289679, 2023).
leukemia (6 papers, 2016 to 2024). A malignant (clonal) hematologic disorder, involving hematopoietic stem cells and characterized by the presence of primitive or atypical myeloid or lymphoid cells in the bone marrow and the blood. "Down regulation of PI3K/AKT signaling using the IAP inhibitor, GDC-0152, which targets BIRC2, BIRC3, and XIAP has been shown to result in the induction of apoptosis in human leukemia cells." (PMID 27074575, 2017).
esophageal squamous cell carcinoma (5 papers, 2004 to 2019). Esophageal squamous cell carcinoma (ESCC) is a type of esophageal carcinoma (EC) that can affect any part of the esophagus, but is usually located in the upper or middle third. "It has recently been reported that BIRC2 is associated with resistance of esophageal squamous cell carcinomas to drug-induced apoptosis and that c-IAP1 could be a novel predictive marker for resistance to radiotherapy in cervical squamous cell carcinomas." (PMID 22523595, 2012). "In eight cases of squamous cell carcinoma of the oesophagus, COX-2 and BIRC2 mRNA expressions of pretreatment biopsy samples were assayed by quantitative RT–PCR." (PMID 15365572, 2004).
gastric cancer (5 papers, 2019 to 2022). A primary or metastatic malignant neoplasm involving the stomach. "On the contrary, the overexpression of BIRC2 promotes the metastasis of gastric cancer cells." (PMID 35280928, 2021). "miRNA-204 leads to enhanced BIRC2 expression level and BIRC2/TNF-a/NF-kB signaling pathway activities, which promoted angiogenesis and metastasis of gastric cancer cells." (PMID 36314013, 2022).
nasopharyngeal carcinoma (5 papers, 2010 to 2025). A carcinoma arising from the nasopharyngeal epithelium. "For instance, BRD7 negatively regulated the transcriptional activity and expression of baculoviral IAP repeat containing 2 (BIRC2), which functions as an oncogene in nasopharyngeal carcinoma." (PMID 39580422, 2024). "Moreover, BIRC2 was identified as an oncogene that promotes cell proliferation, G1/S progression, EMT, invasion, and in vivo tumor growth and metastasis in nasopharyngeal carcinoma." (PMID 36788209, 2023).
lymph node metastasis (4 papers, 2016 to 2024). "Using qRT-PCR and IHC, we demonstrated that the overexpression of BIRC2 (cIAP1) and BIRC3 (cIAP2), both located on 11q22.1-q22.2, was associated with lymph node metastasis in OSCC patients." (PMID 29167558, 2017). "Upregulation of both BIRC2 and BIRC3 was significantly associated with lymph node metastasis (p < 0.002 and p < 0.007, respectively)." (PMID 29167558, 2017).
medulloblastoma (4 papers, 2012 to 2022). A malignant, invasive embryonal neoplasm arising from the cerebellum. "cIAP1 and cIAP2-encoding genes (named BIRC2 and BIRC3) are very closely located on chromosome locus 11q22.2, a region found amplified (11q21 amplicon) in human medulloblastoma, hepatic, breast, pancreatic, cervical, lung, oral squamous cell and esophageal carcinoma." (PMID 35204822, 2022).